CHRNB4 (cholinergic receptor nicotinic beta 4 subunit)
Description:
Component of neuronal acetylcholine receptors (nAChRs) that function as pentameric, ligand-gated cation channels with high calcium permeability among other activities. nAChRs are excitatory neurotrasnmitter receptors formed by a collection of nAChR subunits known to mediate synaptic transmission in the nervous system and the neuromuscular junction. Each nAchR subunit confers differential attributes to channel properties, including activation, deactivation and desensitization kinetics, pH sensitivity, cation permeability, and binding to allosteric modulators. CHRNB4 forms heteropentameric neuronal acetylcholine receptors with CHRNA2, CHRNA3 and CHRNA4, as well as CHRNA5 and CHRNB3 as accesory subunits. CHRNA3:CHRNB4 being predominant in neurons of the autonomic ganglia, it is known as ganglionic nicotinic receptor. CHRNA3:CHRNB4 or CHRNA3:CHRNA5:CHRNB4 play also an important role in the habenulo-interpeduncular tract, modulating the mesolimbic dopamine system and affecting reward circuits and addiction (By similarity). Hypothalamic CHRNA3:CHRNB4 nAChR activation by nicotine leads to activation of POMC neurons and a decrease in food intake (By similarity).
Tractability: Small molecule: an approved drug acts on it; a structure with a bound ligand is known; a high-quality ligand is known; it belongs to a druggable protein family. Antibody: its Gene Ontology location is reachable by antibodies, with high confidence; UniProt places it where antibodies can reach, with medium confidence; UniProt predicts a signal peptide or a membrane-spanning region. PROTAC: a small molecule that binds it is known. Other modalities: a drug acting on it is in phase 2 or 3 trials.
Safety:
Unwanted effects reported when the protein is acted on. In parentheses: how it was acted on, where the effect was seen, and who reports it.
nicotine dependence (source: ClinPGx)
smoking addiction (source: ClinPGx)
Gene: Protein-coding gene on chromosome 15 (78,624,111 to 78,727,754, reverse strand). Ensembl gene ENSG00000117971.
Subcellular location: Synaptic cell membrane; Cell membrane
Subcellular location (Human Protein Atlas): Endoplasmic reticulum; Cell Junctions
Pathways (Reactome):
Neuronal System: Highly calcium permeable nicotinic acetylcholine receptors; Highly calcium permeable postsynaptic nicotinic acetylcholine receptors; Highly sodium permeable postsynaptic acetylcholine nicotinic receptors
Immune System: Neutrophil degranulation
Gene Ontology:
Molecular function: acetylcholine receptor activity; acetylcholine-gated monoatomic cation-selective channel activity; protein binding; ligand-gated monoatomic ion channel activity; extracellular ligand-gated monoatomic ion channel activity; monoatomic ion channel activity; transmembrane signaling receptor activity; transmitter-gated monoatomic ion channel activity involved in regulation of postsynaptic membrane potential
Biological process: acetylcholine receptor signaling pathway; regulation of appetite; signal transduction; synaptic transmission involved in micturition; calcium ion transport; membrane depolarization; monoatomic ion transmembrane transport; monoatomic ion transport; regulation of neurotransmitter secretion; response to acetylcholine; synaptic transmission, cholinergic; chemical synaptic transmission, postsynaptic; excitatory postsynaptic potential; positive regulation of transmission of nerve impulse; regulation of postsynaptic membrane potential
Cellular component: acetylcholine-gated channel complex; cell junction; plasma membrane; synapse; membrane; neuron projection; presynaptic membrane; specific granule membrane; synaptic membrane; tertiary granule membrane; cholinergic synapse; postsynaptic membrane; postsynaptic specialization membrane
Genetic constraint (gnomAD): Loss-of-function variants: 24 observed, 43.7 expected, observed/expected ratio (o/e) 0.55, 90% interval 0.4 to 0.77. The upper end of that interval is the gene's LOEUF score, 0.77, which puts it in group 3 of 6, group 1 being the genes least tolerant of losing a copy. Missense variants: 568 observed, 691.59 expected, observed/expected ratio (o/e) 0.82, 90% interval 0.77 to 0.88. Synonymous variants: 285 observed, 284.77 expected, observed/expected ratio (o/e) 1, 90% interval 0.91 to 1.1.
Homologues: Orthologues: chimpanzee CHRNB4 (98% identical), macaque CHRNB4 (95% identical), guinea pig CHRNB4 (83% identical), mouse Chrnb4 (83% identical), rat Chrnb4 (82% identical), dog CHRNB4 (80% identical), tropical clawed frog chrnb4 (68% identical), zebrafish chrnb4 (63% identical). Paralogues in human: CHRNB2 (63% identical), CHRNA4 (47% identical), CHRNA2 (46% identical), CHRNA3 (45% identical), CHRNA6 (42% identical), CHRNB1 (40% identical), CHRND (39% identical), CHRNB3 (39% identical), CHRNA1 (38% identical), CHRNA5 (38% identical), CHRNG (38% identical), CHRNA7 (35% identical), and 33 more.
Diseases named in the same sentence as CHRNB4 in open-access papers:
CHRNB4 is named in the same sentence as 38 diseases in open-access papers, as found by Europe PMC text mining. Sharing a sentence is not in itself a finding about the gene and the disease. The quoted sentences say what the papers report.
lung cancer (35 papers, 2009 to 2024). A malignant neoplasm involving the lung. "The difference in CHRNA3 rs1051730 and CHRNB4 rs6495309 combination was associated with lung cancer risk in a dose-dependent fashion in discovery (adjusted trend test P = 1.55 × 10−24) and replication (adjusted trend test P = 4.80 × 10−50)." (PMID 30104567, 2018). "In total, for the neuroactive ligand receptor interaction pathway, CHRNA3 rs1051730 and CHRNB4 rs6495309 reached the criterion and were included for further analysis of the independent association and combined effects of SNPs on lung cancer risk." (PMID 30104567, 2018). "A significant dose–response relationship was demonstrated between the number of risk alleles of CHRNB4 rs6495309 and the risk of lung cancer." (PMID 30104567, 2018). "CHRNA5/CHRNA3/CHRNB4 gene cluster is located on chromosome 15q25.1 and was reported to be associated with risk of lung cancer." (PMID 29416783, 2018). "The risk allele of CHRNB4 rs6495309 also significantly increased lung cancer risk in discovery and replication." (PMID 30104567, 2018). "CHRNA3, CHRNA5, and CHRNB4 are subunits of the nicotinic acetylcholine receptor, which contribute to lung cancer risk." (PMID 29207642, 2017). "It was reported that genotype-specific methylation in the promoter of CHRNB4 affected by SNPs that were remarkably corrected with lung cancer risk." (PMID 27926527, 2017). "Given the association between the CHRNA3/CHRNA5/CHRNB4 locus and the risk of lung cancer, attempts have been made to elucidate the pathophysiological role of these three genes encoding α3, α5 and β4 nAChR subunits." (PMID 28978081, 2017). "Multiple genome-wide association studies (GWAS) have implicated the CHRNB4/A3/A5 locus in nicotine dependence and lung cancer." (PMID 24062692, 2013). "Recently, variants in the nAChR genes CHRNA3, CHRNA5, and CHRNB4 have been implicated in nicotine dependence and lung cancer susceptibility." (PMID 24062692, 2013). "Using a case-control study, we decided to investigate the associations between CHRNA3 rs6495308, CHRNB4 rs11072768, smoking behaviors and lung cancer risk, as well as explore whether the two SNPs have a direct or indirect carcinogenic effect on lung cancer." (PMID 26942719, 2016). "Apart from smoke exposure, genome-wide association studies (GWAS) has provided a strong evidence that tobacco-dependent lung cancer patients had a susceptibility region in chromosome 15q25.1, including some genes (CHRNB4, CHRNA3, and CHRNA5) that encode for nicotinic acetylcholine receptors." (PMID 25280560, 2014). "Given the GWAS association between the CHRNB4/A3/A5 locus and lung cancer risk, we pursued the hypothesis that nAChRs containing the α3, α5, and β4 subunits play a direct role in the development of lung cancer." (PMID 24062692, 2013). "While only the nAChR genes on 15q25.1 (CHRNA5, CHRNA3, CHRNB4) have been previously associated with lung cancer risk, there is strong biological rationale to believe that other nAChR genes may influence risk." (PMID 23232035, 2012). "In addition, because rs649530917,18 in CHRNB4 and rs80341912,17 in HYKK had been reported to exhibit the strongest association with lung cancer risk in CHRNB4 and HYKK, separately, we also explored the effect of rs6495309 and rs8034191 on whole-genome gene expression level." (PMID 30104567, 2018). "Consistent research showed CHRNB4 knockdown led to reduced proliferation and propensity to form colonies in lung cancer cells." (PMID 33304845, 2020). "Previously CHRNA3/CHRNA5/CHRNB4 locus and nearby gene PSMA4 have been associated with increased risk of lung cancer." (PMID 30543688, 2018). "Both types of tumors also share a transcriptional dysregulation of the three nAChR subunit genes grouped at the chromosomal locus (15q25.1) that predisposes to lung cancer; gene expression was reduced (CHRNA3) or increased (CHRNA5 and CHRNB4)." (PMID 28978081, 2017).
lung cancer (continued). "The region on 15q25 contains the genes CHRNA3, CHRNA5, CHRNB4, AGPHD1, and IREB2, and numerous GWA have shown evidence of association of this region with COPD, emphysema, lung cancer, and smoking intensity." (PMID 26634245, 2015). "The locus on chromosome 15q25.1 contains three genes that encode nicotinic acetylcholine receptor (nAChR) subunits (CHRNA3, CHRNA5, CHRNB4) whose involvement in tobacco addiction was suggested from studies conducted on larger lung cancer populations." (PMID 21966413, 2011). "We also evaluated whether the functional eQTL analysis identified the same lung cancer-related pathways after removing the HYKK and CHRNB4, which were eQTL related pathways of genes underlying rs16969968, rs6495309, and rs8034191." (PMID 30104567, 2018). "Genome-wide association studies have identified single nucleotide polymorphisms (SNPs) as risk factors for nicotine dependence and lung cancer in genes encoding nAChR subunits (CHRNB3-CHRNA6 and CHRNB4-CHRNA3-CHRNA5 clusters), and in nicotine-metabolizing enzymes (CYP2A6 and CYP2B6)." (PMID 26623516, 2015). "The locus on chromosome 15q25.1, including the nicotinic acetylcholine receptors CHRNA3, CHRNA5 and CHRNB4, showed concordant effect direction between SCZ, lung cancer, and smoking behavior." (PMID 29330379, 2018). "In lung cancer, we have detected the expression of several nAChR subunit genes, in particular CHRNA3, CHRNA5, and CHRNB4." (PMID 24062692, 2013).
nicotine dependence (29 papers, 2010 to 2023). Physical and psychological dependence on nicotine. "Chrna3 is part of a locus on chromosome 15q25 with Chrna5 and Chrnb4, which has also been identified in human GWASs to be associated with smoking-related behaviors and nicotine dependence." (PMID 37295945, 2023). "The CHRNA3/CHRNA5/CHRNB4 gene cluster, encoding for the α3, α5 and β4 nicotinic acetylcholine receptor (nAChR) subunits, has drawn interest due to its implication in nicotine dependence and lung cancer." (PMID 34206324, 2021). "The gene cluster region, CHRNA3/CHRNA5/CHRNB4, encoding for nicotinic acetylcholine receptor (nAChR) subunits, contains several genetic variants linked to nicotine addiction and brain disorders." (PMID 34206324, 2021). "Numerous GWAS have identified the CHRNA5/CHRNA3/CHRNB4 gene cluster as the region harboring the strongest association with nicotine dependence." (PMID 30453884, 2018). "This study shows that rs4887074 C > G, tagging an LD bin associated with CHRNB4 expression is significantly associated with nicotine dependence, the minor G allele conveying a protective effect in GWAS datasets (COGEND, UW-TTURC, SAGE)." (PMID 30453884, 2018). "We have provided evidence that rare variants in CHRNB4 identified in a deep resequencing study of a cohort of nicotine-dependent and control subjects were associated with reduced risk of developing nicotine dependence." (PMID 24804708, 2014). "We previously showed that selected rare variants at 4 conserved residues in CHRNB4 are associated with reduced nicotine dependence risk." (PMID 24804708, 2014). "Sequencing of the neuronal nicotinic receptor genes in cohorts of nicotine dependent cases and controls has also found associations between variants in three nicotinic receptor genes, CHRNA3, CHRNA4 and CHRNB4, with the risk for nicotine dependence." (PMID 24804708, 2014). "Of the SNPs that we found evidence for an association with BP, rs1948 in CHRNB4 has previously been associated with heavy smoking in adulthood, nicotine dependence and with early age of initiation of tobacco and alcohol use." (PMID 23029550, 2012). "We previously undertook pooled sequencing of the coding regions and flanking sequence of the CHRNA5, CHRNA3, CHRNB4, CHRNA6 and CHRNB3 genes and found that rare missense variants at conserved residues in CHRNB4 are associated with reduced risk of nicotine dependence among African Americans." (PMID 24804708, 2014). "Given that β4 is rate-limiting for receptor activity and that single nucleotide polymorphisms (SNPs) in CHRNB4 have been linked to altered risk of nicotine dependence in humans, we were interested in determining the contribution of allelic variants of β4 to nicotine receptor activity in the MHb." (PMID 24478678, 2014). "Thus, our studies support a protective nature for the β4T374I variant in the animal model, in agreement with genome-wide association studies that linked the corresponding SNP T375I in CHRNB4 to decreased risk for nicotine addiction in humans." (PMID 24478678, 2014). "We report the functional impact of rare variants in CHRNB4, and results that demonstrate that incorporating information on the functional consequences can improve the association between genotype and the complex behavioral phenotype of nicotine dependence." (PMID 24804708, 2014). "Rare missense variants in CHRNB4 (T375I and T91I) and in CHRNA3 (R37H) are associated with lower risk for nicotine dependence and fewer cigarettes per day." (PMID 24478678, 2014). "Hartz and colleagues, focusing on the nicotinic receptor subunit genes associated with nicotine dependence (CHRNA5/CHRNA3/CHRNB4 on chromosome 15q25 and CHRNB3/CHRNA6 on chromosome 8p11) investigated the relationship between nicotine dependence and bipolar disorder." (PMID 35893041, 2022). "Second, the neurotransmitter receptors in this pathway (including CHRNA5, CHRNA3, CHRNB4, and CHRND) participate in the biological process by which smoking induces nicotine dependence." (PMID 30104567, 2018).
schizophrenia (4 papers, 2016 to 2018). A major psychotic disorder characterized by abnormalities in the perception or expression of reality. "TCF4 binding sites were also found at other schizophrenia risk loci including the nicotinic acetylcholine receptor cluster, CHRNA5/CHRNA3/CHRNB4 and SETD1A." (PMID 29228394, 2018).
depression (2 papers, 2017 to 2019). "Downregulation of cholinergic signaling in the habenula, including decreased expression of the genes related to cholinergic signaling, such as ChAT, CHT, VAChT, CHRNA3, and CHRNB4, has been demonstrated in an animal model of depression and in suicide victims diagnosed with major depressive disorder." (PMID 30873055, 2019). "Here, we demonstrated that the expression levels of cholinergic signaling genes (CHAT, VACHT, CHT, CHRNA3, CHRNB3 and CHRNB4) were down-regulated in a chronic restraint stress (CRS) rat model of depression, in which rats display depression-like behaviors such as anhedonia and mood despair." (PMID 28420875, 2017).
esophageal squamous cell carcinoma (2 papers, 2020 to 2021). Esophageal squamous cell carcinoma (ESCC) is a type of esophageal carcinoma (EC) that can affect any part of the esophagus, but is usually located in the upper or middle third. "proved that CHRNB4 knockdown can inhibit the proliferation of esophageal squamous cell carcinoma via the Akt/mTOR and ERK1/2/mTOR pathways by cell counting kit-8, cloning formation assay, and Western blot." (PMID 34912722, 2021).
Anxiety (1 paper, 2014). Intense feelings of nervousness, tension, or panic often arise in response to interpersonal stresses. "Although no studies have investigated gene expression changes of Chrnb4 in PTSD or anxiety, variations in this gene were shown to increase sensitivity to nicotine's effects on attention, mood, and vulnerability to tobacco dependence." (PMID 25165739, 2014).
Ataxia (1 paper, 2017). Ataxia refers to impaired coordination of voluntary muscle movement. "In the present experiments, we examined the role of the Chrnb4 gene in three ethanol behaviors: consumption, ataxia, and sedation." (PMID 28381286, 2017). "Similar to results with the balance beam, deletion of the Chrnb4 gene also did not influence ataxia as measured on the dowel test." (PMID 28381286, 2017).
attention deficit-hyperactivity disorder (1 paper, 2022). A disorder characterized by a marked pattern of inattention and/or hyperactivity-impulsivity that is inconsistent with developmental level and clearly interferes with functioning in at least two settings (e.g. at home and at school). "In particular, CHRNB4 has been linked to the modulation of attention in attention deficit/hyperactivity disorder." (PMID 35873773, 2022).
colitis (1 paper, 2019). Inflammation of the colon. "For example, one of the top-ranking triplet prediction is the association among Galantamine, neuronal acetylcholine receptor subunit beta-4 (CHRNB4) and colitis, where the interaction between Galantamine and CHRNB4 is known before the prediction." (PMID 31839008, 2019).
heroin addiction (1 paper, 2024). "A haplotype block across CHRNA5, CHRNA3, and CHRNB4 was linked to changes in sexual desire post-long-term heroin use, highlighting the connection between nAChRs gene polymorphisms and heroin addiction phenotypes in the Chinese Han population." (PMID 38862938, 2024).
hyperglycaemia (1 paper, 2020). "In WT mice, but not in Chrnb4 KO mice, single acute treatment with DMPP induced transient hyperglycaemia, which was accompanied by high plasma adrenaline (epinephrine) levels, upregulated hepatic gluconeogenic genes, and decreased hepatic glycogen content." (PMID 32140744, 2020).